HMGB1 (high mobility group box 1)
Diseases named in the same sentence as HMGB1 in open-access papers (continued):
Sharing a sentence is not in itself a finding about the gene and the disease.
Anxiety (17 papers, 2016 to 2025). Intense feelings of nervousness, tension, or panic often arise in response to interpersonal stresses. "Hmgb1 in the amygdala may play a stronger role in the mechanosensory and emotional-affective components of pain than in associated anxiety-like behaviors." (PMID 37569320, 2023). "siRNA knockdown of HMGB1 in microglia significantly reduced Notch1/Hes-1 pathway proteins and inflammatory factors, highlighting HMGB1’s role in activating the Notch1/Hes-1 pathway and contributing to anxiety-depressive-like behaviors in CRS mice." (PMID 39789446, 2025). "This study explored the role of Hmgb1 in the CeA on sensory, emotional-affective, and anxiety-like pain-related behaviors in male and female rats in a neuropathic pain model." (PMID 37569320, 2023). "For example, AIE causes long-lasting adult increases in alcohol drinking, risky decisions, reward-seeking, and anxiety as well as reduced executive functions that are paralleled by increased HMGB1-TLR brain neuroimmune signaling." (PMID 36781218, 2023). "HMGB1 upregulation in the mPFC was also observed in C57BL/6 J mice 2 weeks after p-IONX when anxiety was detected." (PMID 35974316, 2022). "Behavioral tests revealed that anti-HMGB1 mAb alleviated not only pain sensitization but also anxiety-like behaviors." (PMID 35974316, 2022). "Supportively, we found that systemic anti-HMGB1 mAb simultaneously alleviated anxiety-like behaviors and pain sensitization in p-IONX mice while reducing HMGB1 expression in the CNS." (PMID 35974316, 2022). "In summary, we identified HMGB1 in the mPFC as a determinant factor for the onset and maintenance of comorbid anxiety in neuropathic pain." (PMID 35974316, 2022). "We found that early-onset anxiety was parallel to the upregulation of HMGB1 in the medial prefrontal cortex (mPFC) in mice after p-IONX." (PMID 35974316, 2022). "Here, we found that layer 2/3 pyramidal neurons were hyperactive one week after p-IONX, temporally in parallel to HMGB1 upregulation and anxiety onset." (PMID 35974316, 2022). "Here we investigated the role of high mobility group box 1 protein (HMGB1), a proinflammatory cytokine, in the medial prefrontal cortex (mPFC) in anxiety comorbidity of neuropathic pain." (PMID 35974316, 2022). "Anti-HMGB1 mAb (1 mg/kg) was given intraperitoneally once daily for consecutive 9 days from D7 to D16 after p-IONX when anxiety was established." (PMID 35974316, 2022). "By comparing HMGB1 expression in the brain regions related to anxiety, we found that HMGB1 upregulation in the mPFC was temporally correlated with the early and late onset anxiety after p-IONX and PSL, respectively." (PMID 35974316, 2022). "Taking advantage of local neutralization of HMGB1 by specific mAb, we revealed that HMGB1 in the mPFC not only drives, but also maintains anxiety-like behaviors and aversion after nerve injury." (PMID 35974316, 2022). "Taken together, our results demonstrate the efficacy of systemic administration of anti-HMGB1 mAb on both neuropathic pain and anxiety comorbidity in the mouse model." (PMID 35974316, 2022). "In the present study, we aimed to investigate the role of cerebral HMGB1 in anxiety comorbidity in neuropathic pain." (PMID 35974316, 2022). "Systemic anti-HMGB1 antibody treatment exerted neuroprotective effects preventing postoperative memory deficits and anxiety in aged rats by preventing surgery-induced reduction of phosphorylated cyclic AMP response element-binding protein in the hippocampus." (PMID 27822212, 2016). "In rats, an adolescent intermittent ethanol (AIE) binge drinking model persistently increases brain HMGB1 and its receptors; alters microglia, forebrain cholinergic neurons, and neuronal networks; and increases alcohol drinking and anxiety while disrupting cognition." (PMID 39135668, 2024).
Anxiety (continued). "We report that Hmgb1 knockdown in the right CeA inhibits evoked sensory and emotional responses, but not anxiety-like behaviors, in support of the literature that suggests that Hmgb1 is a pathogenic mediator of pain-related behaviors." (PMID 37569320, 2023). "Local administration of monoclonal antibody against HMGB1 (anti-HMGB1 mAb) and exogenous ds-HMGB1 (the pro-inflammatory form of HMGB1) into the mPFC demonstrated the determinant role of HMGB1 in anxiety, which was supported by that optogenetic inhibition of mPFC pyramidal neurons alleviated anxiety." (PMID 35974316, 2022). "We found that anti-HMGB1 mAb attenuated anxiety-like behaviors in mice of both models." (PMID 35974316, 2022). "Moreover, the analgesic and anxiolytic effects of intraperitoneal injection of anti-HMGB1 mAb justify antagonism of HMGB1 as a promising therapeutic strategy for neuropathic pain with anxiety comorbidity." (PMID 35974316, 2022). "On the other hand, the absence of association of HMGB1 upregulation in the BLA with anxiety and pain sensitization indicates mild contribution of HMGB1 to these two phenotypes." (PMID 35974316, 2022). "Moreover, antagonizing HMGB1 reversed the hyperexcitability of these neurons and attenuated anxiety of mice concurrently, demonstrating a predominant role of HMGB1 in these electrophysiological and behavioral changes." (PMID 35974316, 2022). "In addition to reversing established pain sensitization and anxiety simultaneously, intraperitoneal injection of anti-HMGB1 mAb reduced HMGB1 upregulation and suppressed the hyperexcitability of layer 2/3 pyramidal neurons in the mPFC after p-IONX." (PMID 35974316, 2022). "HMGB1 expression was upregulated in the mPFC temporally in parallel to anxiety onset, rather than in other regions associated with anxiety." (PMID 35974316, 2022). "Highlight the significant role of the HMGB1/TLR4 pathway in chronic stress-induced VHS, anxiety-like behaviors." (PMID 39749341, 2024). "However, whether HMGB1 serves as a causative factor for comorbid mood disorders of neuropathic pain has not been studied, although it has been linked to anxiety states under other pathological conditions." (PMID 35974316, 2022). "Coincidently, HMGB1 infusion in the mPFC induced anxiety and aversion but did not affect pain sensitivity in naïve mice." (PMID 35974316, 2022). "By contrast, local injection of anti-HMGB1 mAb into bilateral BLA where HMGB1 was also upregulated after p-IONX did not affect anxiety onset and pain sensitization." (PMID 35974316, 2022). "Overall, the observed overexpression of HMGB1 and TLR4 could be mediating the anxiety-like behavior observed 2 weeks after NA injection." (PMID 35803999, 2022). "Here we found that attenuation of anxiety after local infusion of anti-HMGB1 mAb in the mPFC was not accompanied with pain alleviation in p-IONX mice and vice versa in mice treated with gabapentin." (PMID 35974316, 2022). "Interestingly, when anxiety-like behaviors were exhibited on D30 PO in PSL mice, a significant upregulation of HMGB1 expression in the mPFC was also detected." (PMID 35974316, 2022). "Therefore, we deduced that HMGB1 in the mPFC induces anxiety rather than pain sensitization by activating neurons in layer 2/3, hence anti-HMGB1 mAb is anxiolytic but not analgesic." (PMID 35974316, 2022). "In the present work, an overexpression of some genes related to inflammation (the pattern recognition receptor TLR4 and the alarmin HMGB1) was found in the hypothalamus of NA treated rats concurrently with the anxiety-like behavior (i.e. at 2 weeks but not at 10 weeks)." (PMID 35803999, 2022). "we conclude that HMGB1 is involved in both the sensory and negative affective consequences of nerve injury by acting in different sites of the nervous system and may serve as a potential therapeutic target for both pain and comorbid anxiety." (PMID 35974316, 2022).
esophageal cancer (17 papers, 2014 to 2025). A primary or metastatic malignant neoplasm involving the esophagus. "Nonetheless, the expression of HMGB1 in esophageal cancer was significantly associated with gross tumor volume (GTV) (P = 0.014) and TNM stage (7th AJCC) (P = 0.028)." (PMID 36260180, 2022). "Findings reveal that TLR2 activation in Barrett’s organoids and oesophageal cancer cells amplifies inflammation and promotes cancer development by causing the secretion of several inflammatory factors, most notably the nuclear protein, HMGB1." (PMID 33922955, 2021). "Another research evaluated how HMGB1 affects the sensitivity of esophageal cancer cells to radiation by controlling the PI3K/AKT/ATM pathway." (PMID 40740483, 2025). "The results showed the depletion of HMGB1 promoted the apoptosis of esophageal cancer cells induced by IR." (PMID 36260180, 2022). "Meanwhile, the addition of PI3K/Akt pathway activator IGF1 enhanced the proliferation of esophageal cancer cells and suppress the weaker effect induced by HMGB1 depression." (PMID 36260180, 2022). "In this study, we aim to detect the internal mechanism of HMGB1 affecting the radio-sensitivity of esophageal cancer cells through PI3K/Akt/ATM pathway." (PMID 36260180, 2022). "But the addition of IGF1 weak the effect of HMGB1 depression on apoptosis increasing of esophageal cancer cells." (PMID 36260180, 2022). "In this study, we aim to detect the internal mechanism of HMGB1 affecting the radio-sensitivity of esophageal cancer cells with PI3K/Akt pathway inhibitor and promoter." (PMID 36260180, 2022). "Esophageal cancer patients with high expression of HMGB1 and p-ATM have a poor prognosis after chemo-radiotherapy." (PMID 36260180, 2022). "HMGB1 protein levels are significantly reduced by iCRT14 in two radioresistant esophageal cancer cells rECA109 and rKyse150, in a context of either with or without ionizing radiation." (PMID 34008469, 2021). "In esophageal cancer patients, neoadjuvant radiation and chemotherapy correlate with increased serum levels of HMGB1 and pulmonary complications." (PMID 31379812, 2019). "Our previous study showed that either a combination of chemotherapeutic agents (5-FU, CDDP and docetaxel) or X-rays induces the release of HMGB1 from human esophageal cancer cell lines." (PMID 25755254, 2015). "This study highlights HMGB1 as a key regulator of esophageal cancer radioresistance, acting via the PI3K/AKT/ATM axis, and suggests that its inhibition could improve radiotherapy outcomes through enhanced cell death and impaired invasion." (PMID 40740483, 2025). "Downregulation of HMGB1 may promote the radio-sensitivity of esophageal cancer cells through regulating PI3K/Akt/ATM pathway." (PMID 36260180, 2022). "Moreover, HMGB1 expression was positively correlated with lymphatic-vessel density in esophageal cancer and intrahepatic cholangiocarcinoma." (PMID 31399104, 2019). "HMGB1 may also be a prognostic factor; its up-regulation within the tumor microenvironment is positively correlated with esophageal cancer patient survival after chemoradiotherapy, although the significance of HMGB1 is still controversial." (PMID 24686897, 2014). "Analysis of HMGB1 and p‐ATM expression was performed on biopsies from patients with esophageal cancer." (PMID 40740483, 2025). "We observed that downregulation of HMGB1 protein resulted in changes in p-AKT and p-ATM expression of esophageal cancer cells." (PMID 36260180, 2022). "The combination of HMGB1 and p-ATM expression can better predict the prognosis of patients with esophageal cancer after chemo-radiotherapy." (PMID 36260180, 2022). "We observed the expression of HMGB1 and p-ATM in biopsies of esophageal cancer patients with immunohistochemical staining." (PMID 36260180, 2022). "Previous studies have reported miR-495-3p could target CDK1, cadherin 2, and HMGB1 to display its functional role in various cancers, and BUB1 was demonstrated as the direct target of miR-495-3p in esophageal carcinoma." (PMID 40420658, 2025).
esophageal cancer (continued). "In conclusion, we found a combination of HMGB1 and p-ATM may predict the prognosis of esophageal cancer patients with chemo-radiotherapy." (PMID 36260180, 2022). "The absence of correlation between HMGB1 in the tumor microenvironment and immune infiltrate has also been reported in both breast and esophageal cancers." (PMID 31379812, 2019).
lung disease (17 papers, 2014 to 2025). "Oxidative stress initiates the accumulation of extracellular HMGB1 in a number of lung diseases and highly elevated levels of extracellular HMGB1 are associated with ALI, multiple organ failure and poor clinical outcome in patients." (PMID 32024151, 2020). "Further exploration of molecular mechanisms underlying the function of HMGB1 in lung diseases will provide novel preventive and therapeutic strategies for lung diseases." (PMID 28039939, 2017). "Accumulating data have demonstrated that HMGB1 is crucially implicated in lung diseases and acts as independent biomarker and therapeutic target for related lung diseases." (PMID 28039939, 2017). "Elevated sputum HMGB1 was correlated to 10% increased risk of lung function decline, whereas the increase in serum HMGB1 was associated with 5% increased risk of pulmonary disease progression." (PMID 28039939, 2017). "This study raises a possibility that S100 proteins act as DAMPs to mediate inflammatory responses and contribute to indium-induced lung diseases as well as HMGB1 and DNA." (PMID 39516272, 2025). "Since (s)RAGE acts as a major mediator in pulmonary disease, we investigated the capacity of sRAGE and its ligand, HMGB1 to predict future incidence of SSc-related pulmonary complications." (PMID 37409127, 2023). "Accordingly, we investigated the role of airway epithelial cell-derived HMGB1 in the pathogenesis of muco-obstructive lung disease in Scnn1b-transgenic (Scnn1b-Tg+) mouse, a model of human CF-like lung disease." (PMID 36741411, 2022). "The Scnn1b-Tg+ (Tg+) mouse, a model of human CF-like lung disease, also exhibits elevated levels of HMGB1 in BALF." (PMID 36741411, 2022). "To determine the effect of airway epithelial cell-specific HMGB1 deletion on airway epithelium in Tg+ lung disease, we compared the epithelial cell composition in the four experimental groups." (PMID 36741411, 2022). "The results from this study provide novel insights into the role of airway epithelial cell-derived HMGB1 in the pathogenesis of CF-like lung disease in Tg+ mice." (PMID 36741411, 2022). "Collectively, our findings provide novel insights into the role of airway epithelial cell-derived HMGB1 in the pathogenesis of CF-like lung disease in Tg+ mice." (PMID 36741411, 2022). "In pulmonary disease, especially pathologies involving pathogen exposure, respiratory epithelial cells, and infiltrating leukocytes release large amounts of HMGB1, which acts as an early regulator of innate immunity and inflammation." (PMID 34621188, 2021). "Subsequently, the excessive accumulation of extracellular HMGB1, particularly airway and sputum HMGB1, has been reported in a variety of lung diseases." (PMID 32024151, 2020). "Here, we will review the basics of HMGB1 and focus on the current understanding of connections between HMGB1 and lung diseases and its potential as a therapeutic target." (PMID 28039939, 2017). "The deficiency of HMGB1 in airway epithelial cells did not alter some hallmark features of Tg+ lung disease including mucus obstruction and airway epithelial remodeling." (PMID 36741411, 2022). "The epigenetic modulation by miRNAs of the HMGB1 gene is involved in pulmonary disorders." (PMID 35269471, 2022). "This review aimed to summarize our current understanding of the role of HMGB1 in lung diseases." (PMID 28039939, 2017). "Furthermore, we discuss the potential role of HMGB1 in a variety of lung diseases." (PMID 28039939, 2017). "The role of High-mobility group box-1 protein (HMGB1) in mediating inflammation, oxidative stress, and the endothelial- or epithelial-mesenchymal transition in SSc-related lung disease has been highly debated." (PMID 40370719, 2025). "Published studies have described that serum HMGB-1 circulating levels were increased in active TB patients compared to other lung disease or healthy controls, whereas in the same study no statistical differences were seen between the active TB and latent TB patients." (PMID 31818258, 2019).
lung disease (continued). "Overall, the results of this study suggest that the inhibition of the bioactivity of HMGB1 by ODSH could represent a novel, targeted approach for increasing bacterial clearance in CF and non-CF related lung diseases." (PMID 34271850, 2021).
Multiple Organ Failure (17 papers, 2010 to 2025). A progressive condition usually characterized by combined failure of several organs such as the lungs, liver, kidney, along with some clotting mechanisms, usually postinjury or postoperative. "HMGB1 and nucleosomes could be early mediators of excessive immune activation in liver transplantation and indicate the risk of multiple organ failure and death." (PMID 36944948, 2023). "The HMGB1-LPS complex is transported to the endolysosomal system, where it promotes HMGB1 release and severe inflammation, potentially resulting in multiple organ failure." (PMID 40430548, 2025). "Increased HMGB1 levels in serum or plasma reflect systemic inflammation and multiple organ failure and thus are considered to be a predictor of death." (PMID 25032709, 2014). "The inhibition of HMGB1 secretion or activity prevents endotoxin- or bacteremia-induced multiple organ failure." (PMID 20628562, 2010). "HMGB-1 drives the inflammatory cascade and the following multiple organ failure." (PMID 35746047, 2022). "Apoptosis of lymphocytes and dendritic cells releases a large number of DAMPs (including HMGB1, cfDNA, and histone), which leads to cytokine storm, immunosuppression, and coagulation activation, and ultimately ending with multiple organ failure (such as liver, heart, and brain)." (PMID 36444630, 2022). "HMGB1 neutralization is associated with bacterial translocation during acetaminophen hepatotoxicity; blockade of HMGB1 may present a novel therapy to prevent multiple organ failure from gut bacterial translocation in APAP overdose." (PMID 24708589, 2014). "The role of HMGB1 in promoting apoptosis has been confirmed in various diseases, high levels of HMGB1 in ALF patients/animals contributed to inflammatory response and multiple organ failure, serving as a bridge between hepatocyte injury and disease pathogenesis." (PMID 35000581, 2022).